RPS10-NUDT3 (RPS10-NUDT3 readthrough)
Gene: Protein-coding gene on chromosome 6 (34,284,887 to 34,426,071, reverse strand). Ensembl gene ENSG00000270800.
Genetic constraint (gnomAD): Loss-of-function variants: 9 observed, 41.83 expected, observed/expected ratio (o/e) 0.22, 90% interval 0.13 to 0.38. The upper end of that interval is the gene's LOEUF score, 0.38, which puts it in group 1 of 6, group 1 being the genes least tolerant of losing a copy. Missense variants: 246 observed, 387.88 expected, observed/expected ratio (o/e) 0.63, 90% interval 0.57 to 0.7. Synonymous variants: 123 observed, 139.46 expected, observed/expected ratio (o/e) 0.88, 90% interval 0.76 to 1.02.